LEF1 (lymphoid enhancer binding factor 1)
Diseases named in the same sentence as LEF1 in open-access papers (continued):
Sharing a sentence is not in itself a finding about the gene and the disease.
esophageal cancer (5 papers, 2019 to 2025). A primary or metastatic malignant neoplasm involving the esophagus. "The transcription factors LEF1, TEAD4, OCT4 and other molecules promote the biological behavior of esophageal cancer, and are associated with poor prognosis of esophageal cancer patients." (PMID 36611908, 2022). "While LEF1 overexpression has been observed in various cancer cells and extensively studied for its altered function, its involvement in cancer stroma was only documented in a publication where Lef1 expression was increased in murine dermal fibroblasts cocultured with human esophageal cancer cells." (PMID 39887653, 2025). "The results showed a significant correlation between the expression levels of SPINK5 and β‐catenin (CTNNB1), LRP5, LRP6, DVL3, LEF1, AXIN2, MYC, and cyclin D1 (CCND1) in esophageal cancer." (PMID 30868765, 2019).
lymphoma (5 papers, 2012 to 2020). A malignant (clonal) proliferation of B- lymphocytes or T- lymphocytes which involves the lymph nodes, bone marrow and/or extranodal sites. "Loss of Tcf1 as repressor of Lef1 leads to high Wnt activity and is the initiating event in lymphoma development, which is exacerbated by activating Notch1 mutations." (PMID 23185135, 2012). "In the E2A-deficient lymphomas, Lef1 is a Notch target gene only in the context of the lymphoma cells, but not in normal progenitors, and Lef1 is essential for lymphomagenesis." (PMID 23185135, 2012). "The expression level of Lef1 was increased in both Tcf1−/− induced lymphomas, indicating that these high levels of Lef1 underlie the highly active Wnt signals in these tumors." (PMID 23185135, 2012). "As high Lef1 expression is already present in pre-leukemic samples, it is likely that deregulated Wnt signaling predisposes thymocytes to induction of activating somatic mutations in Notch1, which subsequently accelerate lymphoma development." (PMID 23185135, 2012). "Taken together, these data indicate that the highly deregulated Wnt signaling in the tumor cells is driven by Lef1; that it is frequently associated with increased Notch signaling, which acts as a collaborative oncogenic event; and that it is continuously required for survival of these lymphomas." (PMID 23185135, 2012). "These lymphoma cells had high Lef1 levels and were highly sensitive to β-catenin and Srebf2-cholesterol synthesis inhibitors." (PMID 32985581, 2020). "Lef1 expression can be further enhanced by Notch, as shown in lymphomas that lack the E2A transcription factor." (PMID 23185135, 2012). "We propose that Tcf1−/− blocked thymocytes give rise to lymphoma cells due to deregulated Wnt signaling, which is driven by expression of deregulated expression of Lef1." (PMID 23185135, 2012). "LEF1 mutations have been identified and associated with high-risk events in AML and lymphoma." (PMID 25942645, 2015). "Once Notch1 expression is established, it may serve as an accelerator of the Lef1-mediated deregulated Wnt signaling, ensuring increased survival and expansion of the lymphoma cells." (PMID 23185135, 2012). "Moreover, the high Axin2 expression in the majority (73%) of lymphomas in combination with the universally up-regulated Lef1 expression indicates a marked increase in Wnt signaling in these lymphomas." (PMID 23185135, 2012). "In addition, transfection of a dominant negative form of Tcf1/Lef1 in Tcf1−/− lymphoma cells also induced rapid cell death (>80% cell death after 6 h)." (PMID 23185135, 2012). "LEF1 expression was reported to be elevated in adult ALL, CLL/lymphoma and AML." (PMID 25942645, 2015). "We established that both TCF1 and LEF1 interact with ATF2 transcription factors to promote TCF/LEF activity, and inhibition of such activity using either DN-TCF4 or shATF2/7 decreased the expression of Wnt target genes, as well as lymphoma cell growth." (PMID 23966864, 2013). "Thus, the lymphoma development is initiated by developmental arrest due to lack of Tcf1; thereby, the suppression of Lef1 expression by short Tcf1 isoforms is lifted." (PMID 23185135, 2012).
mantle cell lymphoma (5 papers, 2020 to 2023). Mantle cell lymphoma is a rare form of malignant non-Hodgkin lymphoma affecting B lymphocytes in the lymph nodes in a region called the ``mantle zone''. "Strongly increased MCL (mantle cell lymphoma) from CLL is caused by LEF-1–, and LEF– also decreases the survival of CLL." (PMID 36050343, 2022).
nasopharyngeal carcinoma (5 papers, 2020 to 2024). A carcinoma arising from the nasopharyngeal epithelium. "Another study revealed that LEF1 was associated with positive clinical progression, suggesting it as an independent biomarker to predict poor prognosis for nasopharyngeal carcinoma." (PMID 35251139, 2022). "Importantly, increased LEF1 is also observed in latent-EBV-associated cancers including Burkitt lymphoma, nasopharyngeal carcinoma, and gastric carcinoma." (PMID 38113273, 2023). "Elevated LEF1 levels are also observed in nasopharyngeal carcinoma and Burkitt lymphoma." (PMID 38113273, 2023). "Elevated levels of LEF1 have been observed in various EBV-positive cancers such as Burkitt lymphoma and nasopharyngeal carcinoma, as well as following EBV latent infection of the human telomerase-immortalized normal oral keratinocyte cell line (NOK)." (PMID 38113273, 2023).
non-small cell lung carcinoma (5 papers, 2017 to 2024). A group of at least three distinct histological types of lung cancer, including non-small cell squamous cell carcinoma, adenocarcinoma, and large cell carcinoma. "Furthermore, downregulation of E-cadherin and nuclear translocation or activation of β-catenin/LEF-1, a major signaling event occurring in EMT, was found associated with FUT8 upregulation during non-small cell lung cancer progression." (PMID 28982386, 2017). "In non-small cell lung cancer, DEPDC1B could enhance cell migration and invasion through the activation of Wnt/β-catenin signaling, and this biological effect could be inhibited by the depletion of LEF1 or TCF4." (PMID 35095994, 2021).
Stroke (5 papers, 2014 to 2025). Sudden impairment of blood flow to a part of the brain due to occlusion or rupture of an artery to the brain. "LEF1, a brain endothelium-specific transcription factor, has been associated with vascular remodeling and post-stroke angiogenesis, and SMARCA4 with cardio–cerebral–peripheral vascular diseases in GWAS." (PMID 35008743, 2021).
adenoma (4 papers, 2003 to 2024). A neoplasm arising from the epithelium. "The loss of Lef1 markedly increased tumor initiation and tumor cell proliferation, reduced the expression of several Wnt antagonists, and increased the Myc proto-oncogene expression and the formation of ectopic crypts in Apc-mutant adenomas." (PMID 39200196, 2024). "Loss of Lef1 markedly increased tumor initiation and tumor cell proliferation, reduced the expression of several Wnt antagonists, and increased Myc proto-oncogene expression and formation of ectopic crypts in Apc-mutant adenomas." (PMID 34788095, 2021). "However, as we have analyzed here the function of Lef1 only in the Apc-mutant intestines, we cannot conclude whether Lef1 has a similar function in adenomas that have progressed with secondary mutations." (PMID 34788095, 2021). "We analyzed Lef1 expression in Apc-mutant tumors that are ligand independent and in Rnf43;Znrf3-mutant adenomas that are ligand dependent and have a serrated growth pattern." (PMID 34788095, 2021). "The GSEA analysis of hallmark pathways showed that Myc and its target transcripts in the adenoma cluster were more up-regulated after Apc;Lef1 deletion than after Apc deletion, and immunostaining confirmed a corresponding increase in Myc protein levels." (PMID 34788095, 2021). "On the basis of the similarities of Lef1-deficient Apc-mutant adenomas with Kras-mutant CRC, we propose that Kras and Lef1 act in the same pathway in the process of transformation of ISCs to promote (Kras) or reduce (Lef1) the fixation of mutated crypts." (PMID 34788095, 2021). "Overall, the immunostaining and scRNA-seq data demonstrate that Lef1 inactivation increases the proportion of Apc-mutant adenoma cells that have a high Wnt signaling activity." (PMID 34788095, 2021). "We found a substantial increase in Lyz1+ cells and doublets of Lyz1+ and Lgr5+ cells that appeared to form intestinal crypt-like structures in β-catenin+ adenomas after Lef1 deletion." (PMID 34788095, 2021). "scRNA-seq analysis of the LApc and LApcL adenoma cells confirmed the increased expression of Msx1 and Lyz1 after Lef1 deletion." (PMID 34788095, 2021). "Overall, our results suggest that Lef1 deletion favors dedifferentiation toward the ISC phenotype in the adenomas, and increases the number of ectopic crypts that are critical for CRC growth." (PMID 34788095, 2021). "We found that Lef1 deletion increased Lyz1+ cells but, unexpectedly, decreased Lgr5+ stem cells in the LApcL adenomas." (PMID 34788095, 2021). "Our finding that the number of aberrant crypt foci and adenoma cells was increased in the LApcL mice suggests that also Lef1 deletion increases crypt fixation." (PMID 34788095, 2021). "The Wnt/TA cell population comprised 70% of all EpCAM+ cells in the LApcL intestine but only 33% in the LApc intestine and 28% in the adjacent normal tissue, indicating that Lef1 deletion led to an increase in adenoma cells." (PMID 34788095, 2021). "Histopathological analysis showed that the Lef1-deleted adenomas had increased dysplasia, which is a known feature in Kras-mutant adenomas." (PMID 34788095, 2021). "Immunofluorescence analysis confirmed a corresponding decrease in the Lgr5-GFP+ tumor cell area and Sox9+, Prox1+, and Cd24+ adenoma cells in the intestinal sections 18 days after Lef1 deletion." (PMID 34788095, 2021). "Although Lef1 deletion in the tumors decreased the number of Lgr5+ adenoma stem cells, it simultaneously increased the number of ectopic stem cell niches." (PMID 34788095, 2021). "Perhaps, because of functional redundancy between members of Tcf/Lef family, we detected compensatory increase in Tcf7 or Tcf7l2 transcripts in the Lef1 deleted adenoma cells." (PMID 34788095, 2021). "Consistent with our data indicating a role for Lef1 in suppressing ectopic crypt formation, the TSAs accumulate more ectopic crypts than conventional Apc-mutant adenomas." (PMID 34788095, 2021).
adenoma (continued). "We found that approximately 10 and 40% of Lgr5+ cells were located next to Lyz1+ cells in the LApc and LApcL adenomas, respectively, suggesting that the Lgr5+ ISCs give rise to the strongly increased ectopic crypts after Lef1 deletion." (PMID 34788095, 2021). "Some of the phenotypic properties of Lef1-deleted Apc-mutant adenomas resembled those described in Apc;Kras-mutant mice." (PMID 34788095, 2021). "Staining of Lef-1 was confined to the cytoplasm and cell borders of these cells and in the epithelial-derived tumour cells of two benign adenomas, two borderline tumours." (PMID 14520463, 2003). "In normal cells, two LEF1 isoforms regulate Wnt-dependent pathways as apoptosis, motility, and gene transcription, and its expression in human colon tissue gradually increased from a normal colon, low-grade adenoma, high-grade adenoma, to adenocarcinoma." (PMID 39200196, 2024). "Moreover, we found decreased LEF1 expression in the CMS3 and CRISA subtypes of CRC, which are characterized by KRAS mutations and in serrated adenomas, which typically harbor KRAS/Serine/Threonine-Protein Kinase B-Raf (BRAF) mutations." (PMID 34788095, 2021). "Stromal and niche factors, such as increased vasculature, could contribute to the in vivo growth of Lef1-deleted adenomas; they remain to be analyzed in further studies." (PMID 34788095, 2021). "Furthermore, Rnf43 and Znrf3 transcripts decreased significantly in the Lef1-deleted adenoma cells concomitantly with decreased expression of Wnt antagonists." (PMID 34788095, 2021). "In our study, LEF1 is highly expressed in the adjacent mucosa and decreased in the polyp, supporting the recent hypothesis of LEF1’s role as a tumor suppressor, already in adenomas, but also its essential role in stem cell maintenance during crypt formation and organ development." (PMID 39200196, 2024). "Similar to Lef1 deletion, oncogenic KRAS has been shown to induce Myc and Cd44 expression and increase the dedifferentiation of the adenomas." (PMID 34788095, 2021). "Furthermore, a comparison of LApc and LApcL adenoma cells in GSEA pathway analysis showed a significant increase in mTorc1 and Pi3K-Akt/mTor signaling and a decrease in Tgfβ signaling after Lef1 deletion." (PMID 34788095, 2021). "We first confirmed that in situ hybridization detects Lef1 expression in the Apc adenomas but not in adjacent normal tissue." (PMID 34788095, 2021). "Although Apc-mutant adenomas are independent of Wnt ligands, we found that several Wnt antagonists were decreased after Apc;Lef1 deletion." (PMID 34788095, 2021). "We show that Lef1 is expressed in Wnt ligand–independent Apc-mutant adenomas, but not in Wnt ligand–dependent Rnf43;Znrf3-mutant intestine." (PMID 34788095, 2021). "The tumor promoting phenotype of Lef1 deleted adenoma cells was not recapitulated in organoid cultures, indicating that the phenotype is not cell autonomous." (PMID 34788095, 2021). "However, overexpression of RAC1B did not increase the number of proliferative cells in the normal small intestine nor in the early adenomas and did not increase the expression of canonical Wnt target genes such as Axin2, Tcf7, Lef1 or Ctnnb1." (PMID 34564693, 2021). "Furthermore, we found that in contrast to Wnt ligand–independent Apc-mutant adenomas, Lef1 was not expressed in Wnt ligand–dependent serrated adenomas." (PMID 34788095, 2021). "Our results uncover a previously unknown negative feedback mechanism in CRC, in which ectopic Lef1 expression suppresses intestinal tumorigenesis by restricting adenoma cell dedifferentiation to a crypt-progenitor phenotype and by reducing the formation of cancer stem cell niches." (PMID 34788095, 2021).
breast tumor (4 papers, 2015 to 2025). "Additionally, to further confirm whether Wnt1-positive breast tumor cells represent an LEF1-positive subpopulation, we investigated the co-expression of these markers in tumor xenografts." (PMID 26202299, 2015). "Since we identified LEF1 expression in exp‐CAF 544 cells, we proceeded to investigate the presence of LEF1‐positive CAFs in the stroma of human breast tumor specimens by immunohistochemistry." (PMID 39887653, 2025). "LEF1 enhancer facilitated Wnt pathway in tumor invasion, while LRRC15 protein, which was usually over-expressed in tumor, particularly breast tumors, was reported as a potential drug target for virus based cancer therapy." (PMID 28950860, 2017).
colorectal tumor (4 papers, 2010 to 2022). "Furthermore we obtained evidence for a role of LEF-1 and TCF4 as independent prognostic variables of clinical outcome in colorectal tumour patients." (PMID 21092222, 2010). "In summary, we found LEF-1 expression in 26% and TCF4 in 46% of colorectal tumours." (PMID 21092222, 2010).
medulloblastoma (4 papers, 2014 to 2025). A malignant, invasive embryonal neoplasm arising from the cerebellum. "For instance, the CTNNB1 gene mutation can result in 90% WNT-activated medulloblastoma, which can induce alterations in the amino acid residues at the phosphorylation site of β-catenin, and LEF1 can form a transcriptional complex with β-catenin in the nucleus." (PMID 39881334, 2025). "LEF1 immunohistochemistry has been recognized as a more reliable diagnostic biomarker than β-catenin for identifying WNT-activated medulloblastoma subtypes." (PMID 39851951, 2025). "In medulloblastoma, LEF1 upregulation is associated with the WNT-subtype." (PMID 39851951, 2025). "Among the LEF1 targets upregulated in WNT medulloblastoma, 13 genes were identified as regulators of the WNT pathway." (PMID 39851951, 2025). "During this study, the transcription factor LEF1 was found to be commonly upregulated in hepatoblastoma and medulloblastoma tumors." (PMID 39851951, 2025). "LEF1 target genes, identified through ChIP-sequencing as 2039 promoter regions, were mapped onto the transcriptome data of medulloblastoma samples in the PBTA cohort." (PMID 39851951, 2025). "LEF1 was found to be significantly increased in the transcriptomes of WNT subtype medulloblastomas compared to other subtypes (ANOVA p ≤ 2 × 10−16), predominantly in samples categorized as primary tumors." (PMID 39851951, 2025). "Principal component analysis (PCA) based on the expression of these 141 LEF1 target genes effectively stratified WNT subtype tumors from other medulloblastoma subtypes." (PMID 39851951, 2025). "These roles, however, remain incompletely understood, particularly in the context of a shared LEF1-mediated transcriptional program across hepatoblastoma and medulloblastoma." (PMID 39851951, 2025). "While LEF1 deregulation in hepatoblastoma remains poorly understood, in the PBTA medulloblastoma cohort, high LEF1 expression was specifically associated with the WNT subtype." (PMID 39851951, 2025). "Immunohistochemical staining of LEF-1 can be used as a supplement for β-catenin to diagnosis WNT-activated Medulloblastomas, when β-catenin is difficult to recognize for its cytoplasm/membrane staining background." (PMID 36096860, 2022). "Consequently, LEF1 is also an excellent auxiliary marker for diagnosing WNT-activated medulloblastoma." (PMID 39881334, 2025). "The ROC curve analysis of the combined expression of these 13 WNT-related LEF1 target genes confirmed their ability to predict the WNT subtype in medulloblastoma, achieving an AUC of 1.00 with 100% specificity and 100% sensitivity in the PBTA medulloblastoma cohort." (PMID 39851951, 2025). "Thus, immunohistochemical staining of LEF-1 can be used as a supplement for β-catenin to diagnosis WNT-activated Medulloblastomas, when β-catenin is difficult to recognize for its cytoplasm/membrane staining background." (PMID 36096860, 2022). "Transcripts contributing significantly to these enrichments encoded WNT16, DKK1 and LEF1 that are specifically over-expressed in WNT medulloblastoma irrespective of developmental control comparison." (PMID 25412507, 2014). "Together, these TFs interact in oncogenic networks where LEF1 serves as a central effector of WNT signaling, underscoring the intricate transcriptional landscape driving tumorigenesis in hepatoblastoma and medulloblastoma." (PMID 39851951, 2025). "ElasticNet coefficients highlighted the predictive importance of genes such as AXIN1, RNF43, STK3, LEF1, and DKK1 for identifying the WNT subtype status in this medulloblastoma validation cohort." (PMID 39851951, 2025). "This study aims to bridge this gap by investigating the common transcriptional and molecular features driven by LEF1 in both hepatoblastoma and WNT-subtype medulloblastoma." (PMID 39851951, 2025).
medulloblastoma (continued). "The ROC curve analysis of the combined expression of these 13 WNT-related LEF1 targets yielded an area under the curve (AUC) of 1.00, indicating 100% specificity and sensitivity for predicting the WNT subtype in the PBTA medulloblastoma cohort." (PMID 39851951, 2025). "In accord with previous reports, we identified distinct groups of co-expressed genes that were highly enriched for WNT signalling in WNT medulloblastoma, (including DKK1, DKK2, DKK4, WIF1, LEF1 and WNT16)." (PMID 25412507, 2014). "Using the expression profiles of these 13 WNT-related LEF1 target genes, unsupervised clustering (Euclidean distances and the Ward.D2 method) effectively stratified WNT-medulloblastoma samples from some samples in other medulloblastoma subtypes in the PBTA cohort." (PMID 39851951, 2025).